IL6 (interleukin 6)
Diseases named in the same sentence as IL6 in open-access papers (continued):
Sharing a sentence is not in itself a finding about the gene and the disease.
anemia (continued). "The overproduction of IL-6 and upregulation of IL-6 receptor expression can stimulate the proliferation of B lymphocytes, restrain the expression of vascular endothelial growth factor, and result in a series of systemic symptoms such as fever, anemia, hypoproteinemia and proteinuria." (PMID 31439011, 2019). "However, high hepcidin expression may not only be due to IL-6 activity, as other cytokines may also contribute to anaemia in ACD." (PMID 31683939, 2019). "Multiple factors including psychological factors are involved in dialysis-related fatigue, such as anemia, hemodynamic instability, presence of cardio- and cerebrovascular diseases, nutritional status, and inflammatory conditions accompanying increased levels of hsCRP and IL-6, and TNF-α." (PMID 28902900, 2017). "Previous studies have reported higher circulating IL-6 in frail elderly compared with their non-frail counterparts, associated with low walking speed, poor muscle strength, poor lower extremity performance, and anemia." (PMID 27119508, 2016). "Thus, the relatively low serum hepcidin-25 levels in patients with RA-anemia may partially be due to a balance between opposing effects of hepcidin-regulating cytokines such as IL-6 and TNF-α." (PMID 24286116, 2013). "Anaemia can also be partially linked to inflammation via non-specific erythrophagocytosis by macrophages hyperactivated by chronic inflammation, and also via the IL-6 induced production of hepcidin, an iron regulatory hormone." (PMID 24130501, 2013). "In particular the production of endogenous pyrogens such as TNF, IL-1β and IL-6 following IFN-γ stimulation of monocytes/macrophages may be responsible for fever induction and sustained IL-1β production may be associated with anaemia." (PMID 23046548, 2012). "In summary, we infer that strain-directed IL-6, IFN-γ, and IL-12 responses likely contribute to the acute and chronic anemia observed in infected monkeys." (PMID 41602558, 2026). "Treatment with siltuximab, an IL-6-blocking antibody, mitigated AML-induced anemia and BM failure, thereby extending overall survival in mouse models." (PMID 41550719, 2026). "Treatment-induced tissue damage elevates circulating mediators (C-reactive protein [CRP], IL-6, interleukin-1β [IL-1β], interferon [IFN], tumor necrosis factor-α [TNF-α] potentially mediating central fatigue through anemia and cachexia pathways." (PMID 40496975, 2025). "Laboratory results obtained at follow-up (9 July 2025), showing persistent microcytic anaemia, normal inflammatory biomarkers (hs-CRP and interleukin-6), stable renal function, and lipid profile within acceptable limits for age." (PMID 41362385, 2025). "Chronic inflammation, typical of RA, facilitates the onset of anemia via increased concentrations of pro-inflammatory cytokines, including TNF-α and IL-6." (PMID 40385581, 2025). "CRP production (primarily regulated by IL-6 and indirectly by TNF-α) and TNF-α’s direct suppression of erythrocyte progenitor cell proliferation both contribute to anemia." (PMID 41179861, 2025). "Hemoglobin levels were inversely correlated with IL-6 (r = −0.29, p < 0.01), NLR (r = −0.306, p < 0.01), and PCT (r = −0.249, p < 0.05), further suggesting that systemic inflammation contributes to anemia." (PMID 40430148, 2025). "At initial presentation, all patients showed leukocytosis (WBC: 13.41–28.2 × 10^9/L), thrombocytosis (PLT: 359–594 × 10^9/L), anemia (HGB: 62–110 g/L), and elevated inflammatory markers (CRP: 100–166.68 mg/L; ESR: 19–112 mm/h; IL-6: 32.51–58.4 pg/mL)." (PMID 40859316, 2025). "KICS is a newly described condition that typically manifests with fever, anemia, thrombocytopenia, hypoalbuminemia, hyponatremia, hepatosplenomegaly, elevated CRP, and increased IL‐6 and IL‐10 levels, along with a high HHV‐8 viral load." (PMID 41424756, 2025). "Anemia can stimulate the production of pro-inflammatory cytokines such as tumor necrosis factor-alpha (TNF-α), interleukin-1 beta (IL-1β), and interleukin-6 (IL-6)." (PMID 40486649, 2025).
anemia (continued). "These include anemia, hypoalbuminemia, and elevated inflammatory markers such as C-reactive protein (CRP) and interleukin-6 (IL-6)." (PMID 39861412, 2025). "Clinically, patients develop fever, night sweats, weight loss, lymphadenopathy, hepatosplenomegaly; laboratory tests demonstrate anemia, hypercreatinine, elevated CRP, IL-6, and hypoalbuminemia." (PMID 41010767, 2025). "Hematopoietic dysfunction is common in FD patients and FD mouse models as shown by splenomegaly, lymphocytosis, neutrophilia, anemia, as well as excess cytokine release in plasma (MCP-1, IL-6) and macrophage infiltration into many organs." (PMID 39108096, 2024). "Inflammatory cytokines, especially TNF-α and IL-6, further exacerbate CKD progression and disrupt iron homeostasis, thereby influencing anemia severity." (PMID 38612557, 2024). "Another randomized, blinded study with patients with non-small-cell lung cancer (NSCLC) (n = 124) showed effectiveness in reducing anemia and CAC after treatment with ALD518, an anti-IL-6 antibody." (PMID 38730660, 2024). "We also observed acutely increased concentrations of IL-6 and hepcidin during the acute attack in correlation with the high levels of CRP and severe anemia." (PMID 39408004, 2024). "Considering that the Il-6 effect is mediated by the JAK-STAT pathway, it has been demonstrated that JAK2-STAT3 inhibitors improve anemia in animal models by reducing hepcidin levels." (PMID 37374094, 2023). "IL-2, sIL-2R, IL-6, IL-8, IL-12, IL-17, MCP-1/CCL2, and MIP-1α correlate with anemia/RBC transfusion dependency while IL-6, IP-10/CXCL-10 and MIP-1β correlate with thrombocytopenia." (PMID 37760903, 2023). "Although the differences were not statistically significant, the characteristics of patients with suboptimal anemia control (Hb < 10 g/dL) and HIS, showed that they tended to have worse preserved RRF and higher levels of ferritin, hepcidin, hsCRP and IL6." (PMID 37484854, 2023). "Other inflammatory parameters such as interleukin-6 (IL-6) and C-reactive protein (CRP) should also be included to provide a more comprehensive picture of the anemia status of the OA children." (PMID 37007386, 2023). "On the other hand, the circulating levels of IL-1β, IL-8, CXCL10, IL-6, CCL4, IL-1RA and CCL2 displayed an inverse behavior, with rising levels being proportional to increases in anemia severity." (PMID 37143662, 2023). "Patients with anemia were significantly older (p < 0.0001), reported more co-morbidities, and presented higher baseline levels of procalcitonin, CRP, ferritin and IL-6." (PMID 37270578, 2023). "Hepcidin and interleukin 6, along with routine blood parameters, were determined and outcomes, such as death, multiple organ damage (MOD), anemia, and need for transfusions, were assessed." (PMID 35883855, 2022). "Although the IL-6 pathway can be inhibited by either IL-6R or JAK inhibitors, our data suggest a more pronounced effect on anemia and inflammation with an anti-IL-6R treatment." (PMID 36544236, 2022). "Considering anemia, the group of SLE-a patients showed a strong correlation of RDW with serum IL-6 (r = 0.894, p < 0.001) in addition to PLR with TNF (r = 0.743, p < 0.025) and an inverse correlation with C3 complement (r = 0.538, p < 0.05)." (PMID 35620179, 2022). "Together, our findings suggest that caffeine decreases hepcidin expression via inhibiting inflammation and the activation of the IL-6/STAT3 pathway, thus presenting an attractive, potential therapeutic for the treatment of anemia of inflammation." (PMID 35888113, 2022). "Among biological findings, anemia, elevated CRP, and IL-6 were also significant predictors for prematurity in association with SARS-CoV-2 infection during pregnancy." (PMID 36579593, 2022). "Firstly, IL-6 has been found to be correlated with ESR, anti-dsDNA antibodies, disease activity, and anemia." (PMID 35620179, 2022).
anemia (continued). "Higher levels of inflammatory markers, interleukin-6, and leptin; hepcidin levels; ferritin levels; EPO levels; and reactive oxygen species (ROS) all contribute to the incidence of anemia in cancer patients." (PMID 35464620, 2022). "Histopathologic lymph node features, anemia, elevated CRP and IL6 levels, splenomegaly, and hypoalbuminemia indicated multicentric Castleman (MCD) disease." (PMID 35399163, 2022). "The odds ratios (ORs) and 95% confidence intervals for elevation (top quartile) of IL-1α, IL-1β, IL-6, IL-8, and CRP in umbilical cord blood are shown for maternal nutrition (anthropometrics and anemia) and infections in pregnancy." (PMID 34836049, 2021). "Inflammatory cytokines secreted by tumors, such as IL-6 and TNF-α, can change the tumor and hematopoietic microenvironment, leading to worsening tumor oxygenation and tumor-related anemia." (PMID 34208273, 2021). "In our population, patients with ACD had significantly higher hsCRP, IL6, fibrinogen and SAA levels when compared to patients with IDA or multifactorial anemia." (PMID 34458328, 2021). "Moreover, hepcidin level may be increased with age, independent of IL-6, if kidneys fail to clear hepcidin efficiently, or if other inflammatory cytokines, such as IL-1α or β induce its production, suggesting that IL-6 and hepcidin possibly led to the development of anemia with age independently." (PMID 32095285, 2020). "Patients with anemia were older, had a reduced renal function, and had significantly higher levels of inflammatory markers such as CRP or IL-6." (PMID 32751400, 2020). "IL-6 and tumor necrosis factor-α (TNF-α) are also important cytokines for the development of tumor-induced anemia." (PMID 29719631, 2018). "But HIV-infected patients with anemia that is resolved with cART had lower levels of IL-8, IL-18, IL-22, MIP-1-β and MCP-1 and higher IL-6 and hepcidin levels than patients with persistent anemia, either at T0 and T1." (PMID 29258550, 2017). "Exploratory literature indicates altered pro-inflammatory makers IL-6, IL-8, TNF-α, treatment-induced anaemia, hypoalbuminemia, and a reduction in lean muscle mass are associated with the prevalence of CRF." (PMID 28895922, 2017). "In anemia of chronic disease (ACD), IL-6 is reported to suppress erythropoiesis by a direct mechanism and by indirect mechanisms mediated by other cytokines." (PMID 27068103, 2016). "Because the anemia in this model was observed to be microcytic, we used the model to investigate iron-related parameters in order to clarify the hypothesis that overproduction of IL-6, a positive regulator of hepcidin, elevates hepcidin levels and disturbs iron metabolism." (PMID 27068103, 2016). "We did not detect any effect of systemic inflammatory biomarkers (e.g., hs-CRP, interleukin 6, and alpha-1-acid glycoprotein (data not shown)) that are often associated with lower serum proteins, including hemoglobin, on the relation between serum thyroglobulin concentration and anemia." (PMID 27455319, 2016). "Tocilizumab improved anemia of inflammation in MCD accompanied by down-regulation of hepcidin, suggesting that IL-6 plays an essential role in the induction of hepcidin in MCD, although multiple factors can affect serum hepcidin levels." (PMID 27068103, 2016). "Laboratory abnormalities include anaemia, thrombocytopenia, hyponatremia, hypoalbuminaemia, and elevations of C-reactive protein (CRP), KSHV viral load, interleukin-6 (IL-6), and interleukin-10 (IL-10)." (PMID 26242311, 2015). "IL-6, together with TNF-α, is an inflammatory cytokine critically involved in chronic disease ́ anemia, the major reason for the low hemoglobin levels in RA patients." (PMID 26177310, 2015). "On the other hand, anaemia of chronic disease can occur in patients with chronic ALD, when hepcidin expression is induced by inflammatory stimuli (e.g. IL-6)." (PMID 24894955, 2014).
anemia (continued). "Given the central role of IL-6 in ACD, it is possible that TCZ therapy would improve anemia more effectively than other biologics." (PMID 24878740, 2014). "The pro-inflammatory state is an essential component of anemia or chronic disease, as TNF-α and IL-6 inhibit erythropoietin production in the kidney and the proliferation of bone marrow erythroid progenitor cells." (PMID 23472188, 2013). "In this study, we evaluated and compared the effects of IL-6 and TNF-α blocking therapies on anemia, disease activity, and iron-related parameters including serum hepcidin in RA patients." (PMID 24286116, 2013). "While IL-6 and INF-γ are known to suppress erythropoiesis, TNF and IL-10 are thought to contribute to the degree of anaemia in children with falciparum malaria." (PMID 23978045, 2013). "The general mechanisms by which these infections lead to anaemia include blood loss, sequestration of red blood cells by the spleen, haemolysis by antibodies, and anaemia of inflammation (via TNF-alpha and IL-6 production)." (PMID 21687688, 2011). "There was a statistically significant correlation (r = 0.74; p<0.0001) between IL-6 levels and anemia, at the individual calf level, regardless of the group." (PMID 39208226, 2024). "Typical laboratory findings in MIS-C include lymphopenia, neutrophilia, thrombocytopenia, moderate anemia, abnormal pathological values of inflammatory markers such as ESR, CRP, fibrinogen, ferritin, PCT, and IL-6, and elevated LDH levels, hypoalbuminemia, and hyponatremia." (PMID 39597816, 2024). "Significant positive correlations were found for OPG with IL-6 and RF in the anemia subgroup, while in the subgroup without anemia, OPG showed a negative correlation with serum iron and a positive correlation with ferritin." (PMID 39684440, 2024). "For example, it is known that inflammatory cytokines like interleukin-6 (IL-6) and tumor necrosis factor-alpha (TNF-alpha) may interfere with iron metabolism and erythropoiesis, leading to anemia of inflammation (AI) or anemia of chronic disease (ACD)." (PMID 39588439, 2024). "The negative correlations between CXCL10 and IL-6 with Hb indicate potential links to anemia and hemolysis in SCD patients, suggesting that higher levels of these biomarkers are associated with worse hematological outcomes." (PMID 39749215, 2024). "There were significant positive correlations between sRAGE and CRP, RF, and anti-CCP antibodies in the subgroup without anemia (with normal Hb level) and with IL-6 in the subgroup with anemia (with low Hb level)." (PMID 39684440, 2024). "In this study, hepcidin-1 mRNA levels were not increased, but rather significantly decreased, in IL-18BP KO compared with WT mice, further indicating that IL-6 is probably not involved in the development of anemia in CpG-induced MAS." (PMID 37074208, 2023). "Comparison between the uncomplicated malaria group and moderate malarial anemia group, and between moderate and severe malarial anemia groups revealed no statistical difference for IL-6 (p = 0.145 and p = 0.167, respectively)." (PMID 36787308, 2023). "Additionally, assessment of the systemic inflammatory markers demonstrated that IL6 and IL17A were progressively increased with duration of anemia demonstrating systemic inflammation in CA mice." (PMID 37234375, 2023). "Blockade of IL-6 has proven highly effective for systemic autoinflammation and anemia but has failed to control neuroinflammation in the 3 cases with this complication." (PMID 37744344, 2023). "The effect of elevated IL-6 levels on the suppression of erythropoiesis in SLE patients was confirmed by other studies, which showed higher serum IL-6 levels in SLE patients with anemia compared to SLE patients without anemia." (PMID 37371554, 2023). "Combining potential cancer-induced anemia therapeutic targets, such as TGF-β, VEGF signaling, hepcidin, IL-6, CD71, CCL2/CCR2, GM-CSF, and exercise, with ICIs could therefore be an effective therapeutic approach." (PMID 37208766, 2023).
anemia (continued). "Since CIS3 is stimulated by other proinflammatory as well as anti-inflammatory cytokines, selectively blocking IL-6 with tocilizumab seems to not be enough to prevent anemia." (PMID 36839968, 2023). "It has been suggested that high IL-6 plasma levels induce hypoferremia by upregulating hepatic hepcidin expression via signal transducer and activator of transcription 3 (STAT3) activation, as well as increasing plasma volume to promote anemia." (PMID 37208766, 2023). "Second, hyperventilation was not contingent on evident and expected potential triggers such as anaemia (expressed by haemoglobin, haematocrit), infection (expressed by WBC, CRP, IL-6, IL-22), hypoxemia (expressed by pO2 and sO2) or pulmonary congestion on physical examination." (PMID 36207364, 2022). "Average serum hepcidin-25 level was more than twice higher in patients with anemia than in those without anemia; similar differences were observed between the groups in serum concentrations of IL-6 and GDF-15." (PMID 35334593, 2022). "Tumor markers (CEA and CA 19.9), anemia markers (hemoglobin, hematocrit and medium corpuscular volume) and inflammatory markers (leukocytes, neutrophils, N/L index, platelets, fibrinogen, C-reactive protein, CRP and IL-6) were also determined." (PMID 36232966, 2022). "Anaemia patients had lower hepcidin concentration (x ̄=99.34 ng/mL) than non-anaemia patients (x ̄=331.43 ng/mL, p = 0.000694), with simultaneously higher IL-6 levels (x ̄=53.72 pg/mL) than non-anaemia patients (x ̄=24.64 pg/mL, p = 0.030727)." (PMID 36612220, 2022). "It was observed from this analysis that the group of individuals with anemia had higher levels of IL-6, TNF- α, and IL-10 cytokines than the individuals without anemia (P < 0.05)." (PMID 35749690, 2022). "Importantly, interleukin-6 (IL-6), interferon-γ (IFN-γ) and GM-CSF were notably unregulated in the mouse model of anemia of inflammation (AI) induced by heat-killed Brucella abortus." (PMID 34980171, 2022). "It has previously been demonstrated that high IL-6 concentrations and a high HIV viral load are associated with anemia in TB/HIV co-infected patients, which supports the notion that IL-6 aggravates anemia in pulmonary TB." (PMID 36014824, 2022). "Levels of inflammatory markers (hepcidin, CRP, AGP and IL-6) were significantly higher in AI as compared to participants without anemia (p < 0.05), and IL-6 was higher in CKD; IL-6 and CRP were also significantly higher in AMC." (PMID 34836070, 2021). "While the pathophysiology of anaemia in COPD is still debated, some authors have suggested that the inflammation of COPD mediated by INF-a, IL-1, IL-6 and IFN-gamma induces changes in iron metabolism, reducing the intestinal absorption of this metal and consequently affecting haematopoiesis." (PMID 33509131, 2021). "In HCV-negative HD patients, anemia markers did not significantly differ in the genotypes IL-6 -572 G/C and IL-6 -597." (PMID 32720970, 2020). "As expected, patients with AI had the highest CRP (8.69 mg/dL, p < 0.001) and IL-6 levels (82.7 ng/L, p = 0.007) when compared to patients with IDA (0.12 mg/dL, 3.4 ng/L, respectively) or unclassified/multifactorial anemia (7.79 mg/dL, 70.3 ng/L, respectively)." (PMID 32751400, 2020). "In the current study serum IL-6 level was strongly correlated with various clinical inflammatory parameters (serum CRP, hemoglobin, and albumin levels), and the prevalence of anemia, hypoalbuminemia, and CRP elevation were significantly greater in the higher IL-6 group than in the other two groups." (PMID 31951598, 2020). "The reason for the increased frequency of anemia in old age may be dysregulation of pro-inflammatory cytokines (CRP, TNF-α, IL-6 etc.)with aging." (PMID 31086504, 2019). "We lacked data on inflammatory markers including ferritin, IL-6, or C-reactive protein to correlated with degree of anemia or hepcidin levels." (PMID 30925172, 2019).